ZNF559-ZNF177 (ZNF559-ZNF177 readthrough)
Gene: Protein-coding gene on chromosome 19 (9,324,174 to 9,382,617, forward strand). Ensembl gene ENSG00000270011.
Genetic constraint (gnomAD): Loss-of-function variants: 19 observed, 20.92 expected, observed/expected ratio (o/e) 0.91, 90% interval 0.63 to 1.33. The upper end of that interval is the gene's LOEUF score, 1.33, which puts it in group 5 of 6, group 1 being the genes least tolerant of losing a copy. Missense variants: 633 observed, 588.72 expected, observed/expected ratio (o/e) 1.08, 90% interval 1.01 to 1.15. Synonymous variants: 220 observed, 197.71 expected, observed/expected ratio (o/e) 1.11, 90% interval 1 to 1.24.